DNMT1 (DNA methyltransferase 1)
Diseases named in the same sentence as DNMT1 in open-access papers (continued):
Sharing a sentence is not in itself a finding about the gene and the disease.
glioma (continued). "These differential histone signatures in normal brain and gliomas are in tune with the overexpression of the maintenance DNA methyltransferase (DNMT1) in the latter." (PMID 25602259, 2015). "Here, we show that the disruption of Dnmt1/PCNA/UHRF1 interactions promotes a global DNA hypomethylation in human gliomas." (PMID 20613874, 2010). "Therefore, ADAMTS9‐AS2 functions as a novel tumour suppressor in glioma, and DNMT1 plays a regulatory role in modulating ADAMTS9‐AS2." (PMID 40387409, 2025). "Therefore, an association exists between DNMT1 and MEG3 promoter methylation, wherein DNMT1 showcased an inverse relationship with MEG3 expression in gliomas." (PMID 40387409, 2025). "Furthermore, inhibiting the DNMT1/STAT3 interaction using peptide competitors significantly reduces glioma cell proliferation." (PMID 39996888, 2025). "Notably, inhibiting the DNMT1/DMAP1 interaction has enhanced glioma cell response to temozolomide, suggesting the potential for targeting these complexes in chemotherapy." (PMID 39996888, 2025). "Thus, the MEG3/DNMT1 axis significantly contributes to human glioma pathogenesis, highlighting its potential as a novel therapeutic target in glioma treatment." (PMID 40387409, 2025). "Additionally, DNMT1 silencing hindered glioma cells' clone formation and proliferation while concurrently inducing apoptosis." (PMID 40387409, 2025). "Furthermore, the proliferation capability of glioma cells was higher in both DNMT1-overexpressing groups compared to the NUP37-depleted group." (PMID 39174498, 2024). "Based on our findings, targeting DNMT1-related demethylation pathways could offer a potential therapeutic strategy for glioma treatment." (PMID 39174498, 2024). "Additionally, the apoptosis ratio of glioma cells in both DNMT1-overexpressing groups was observed to be higher than that in the NUP37-depleted group." (PMID 39174498, 2024). "Notably, DNMT1 overexpression successfully mitigated the impaired proliferation, invasion, and migration of glioma cells instigated by NUP37 depletion." (PMID 39174498, 2024). "TCGA database was utilized to examine the differential expression of DNMT1 in gliomas." (PMID 39174498, 2024). "We noted overexpression of NUP37 and DNMT1 in glioma tissues." (PMID 39174498, 2024). "Kaplan–Meier survival analysis further demonstrated that patients with higher DNMT1 expression levels in glioma exhibited lower overall survival rates, disease-specific survival rates, and shorter progression-free periods compared to patients with lower DNMT1 expression levels." (PMID 39174498, 2024). "DNMT1 overexpression has been observed in a variety of malignant tumors, including gliomas." (PMID 39174498, 2024). "This evidence suggested that DNMT1 might engage in cell proliferation-related pathways to preserve the biological function of certain glioma cells under the condition of NUP37 depletion." (PMID 39174498, 2024). "Furthermore, we identify DNMT1 as a potential biomarker predicting which IDH1mut gliomas are most likely to respond to oncolytic virus." (PMID 37880243, 2023). "We demonstrated the crosstalk between the EZH2/H3K27me3/DNMT1 complex and AP-2α methylation in gliomas, suggesting that AP-2α methylation may be a critical epigenetic mechanism in glioblastoma." (PMID 37330579, 2023). "The miR-21/SP1/DNMT1 positive feedback loop in MSCs triggered by glioma exosomal CD44 could increase MSC exosomal miR-21 to a dozen times that in glioma exosomes, amplifying glioma exosomal immunosuppressive signaling." (PMID 37481646, 2023). "Finally, the EZH2/H3K27Me3/DNMT1 complex mediates the methylation modification of AP-2α gene and maintains low expression of AP-2α in gliomas." (PMID 37330579, 2023). "Moreover, we found that miR-21 inhibitor-Dex complex treatment increased DNMT1 expression in CD45−Ter-119− PDGFR-α+Sca-1+ mouse MSCs infiltrating in glioma, indicating that the miR-21 inhibitor disrupted the miR-21/DNMT1 positive feedback loop in MSCs." (PMID 37481646, 2023).
glioma (continued). "The well-established functions of CAHM, which is also known as colorectal adenocarcinoma hypermethylated, as a prognostic biomarker in colorectal and thyroid carcinoma, and its regulation by DNMT1 in glioma cells, suggest its involvement in glioma grade, subtype, malignant behavior, and prognosis." (PMID 37666951, 2023). "The expression of DNMT1 can predict the sensitivity of gliomas to dexitabine." (PMID 37934565, 2023). "DNMT1 plays a role in glioma growth, apoptosis, and migration." (PMID 36203569, 2022). "Blocking DNMT1 can stop TGF-induced glioma cell growth, migration, and invasion." (PMID 36203569, 2022). "Glioma growth is slowed in vitro and in vivo experiments when a DNMT1 inhibitor is given." (PMID 36203569, 2022). "Decitabine can help patients with glioma who have high DNMT1 expression." (PMID 36203569, 2022). "DNMT1 promoter methylation was present in primary and recurrent gliomas." (PMID 31754358, 2019). "Taken together, these results suggest a role for DNMT1 in STAT6 silencing in glioma." (PMID 31530290, 2019). "Evidence has been presented suggesting that enforced expression of DNMT1 may lead to the abnormal DNA methylation of genes in gliomas." (PMID 30926762, 2019). "Indeed, specific inhibition of DNMT1/STAT3 interaction using peptides competitors also significantly decreased glioma-cell proliferation." (PMID 29449903, 2018). "Additionally, DNMT1 decreases hTERT expression by hypermethylation, resulting in its reduced expression in glioma cells andenhancedgliomachemosensitivity." (PMID 28764788, 2017). "Since low-grade gliomas are often characterized by the glioma-CpG island methylator phenotype (G-CIMP), the high DNMT1 expression level in this tumor group could suggest a causal link to DNA methylation." (PMID 28036297, 2017). "We then asked whether c-Jun phosphorylation is involved in the establishment of global DNA methylation in gliomas through regulation of DNMT1 expression." (PMID 28036297, 2017). "DNMT1 is overexpressed in GBM, causing hypermethylation of various tumor suppressor genes and resulting in a lack of cell growth regulation and higher genomic instability, which eventually leads to a poor prognosis in gliomas." (PMID 29228563, 2017). "Because the DNMT1 gene is differentially regulated by both histone acetylation and histone methylation in gliomas, we speculate that the change in expression of DNMT1 could be the consequence of metabolism changes under riluzole treatment." (PMID 29228563, 2017). "Interestingly, we observed a significant correlation between DNMT1 RNA levels and p-c-Jun in high grade gliomas from TCGA (n=531, Pearson correlation=0.3, Baysian predicted correlation R=0.37 (95%CI 0.21-0.5), Fischer's exact test p= 8,9 x10-5)." (PMID 28036297, 2017). "Here, we showed that DNMT1 was involved in epigenetic repression of miR-141 in glioma cells." (PMID 27121316, 2016). "ADAMTS9-AS2 is regulated by DNMT1 and inhibits the migration of glioma cells." (PMID 26252651, 2015).
glioma (continued). "In addition to DNMT1 downregulation, glioma tumor promoter miR-20a11 expression was upregulated, thereby suggesting a possible association between transmethylase inhibition and miR-20a activity." (PMID 26337869, 2015). "Our data indicated that the use of an unspecific DNMT inhibitor (5aza-2deoxycytidine), a DNMT1 inhibitor (procainamide) or peptides disrupting the DNMT1/PCNA, DNMT1/EZH2, DNMT1/HDAC1, DNMT1/DNMT3b and DNMT1/HP1 interactions promoted or enhanced in vivo tumorigenesis in a mouse glioma model." (PMID 23809695, 2013). "We have assumed that the DNMT1 gene is involved in normal DNA methylation in low grade gliomas." (PMID 22264301, 2012). "In our study, no Dnmt1 deficiency was observed in 9 primary cultured tumor cells and in 82 different glioma biopsies." (PMID 20613874, 2010). "Furthermore, continued investigations into the interaction between NUP37 and DNMT1, as well as their specific signaling pathways and molecular mechanisms, will enhance our understanding of glioma pathogenesis and broaden the therapeutic arsenal for this devastating disease." (PMID 39174498, 2024). "Thus, our results suggest that DNMT1 expression may be a useful biomarker to identify subsets of IDH1mut gliomas that are sensitive or resistant to oncolytic virotherapy." (PMID 37880243, 2023). "In addition to monitoring the expression of TERT and DNMT1 to predict sensitivity to decitabine in gliomas, the miRNA-DNMT1 axis plays an essential role in drug resistance and could be applied to overcome azacitidine resistance." (PMID 35838271, 2022). "In addition, NEAT1/miR-152-3p/chaperonin containing the TCP1 subunit 6A (CCT6A) axis 121 and NEAT1/miR-139-5p/CDK6 axis 122 were shown to inhibit cell apoptosis, while the NEAT1/miR-185-5p/DNA methyltransferase 1 (DNMT1) axis 123 promoted EMT in glioma cells and inhibited cell apoptosis." (PMID 34512157, 2021). "Hence, we detected the expression of DNMT1 in glioma cells at both protein and mRNA levels." (PMID 32226508, 2020). "Thus, we conclude that the loss of DNMT1/UHRF1/PCNA and the APOBEC3γ overexpression are the two leading molecular causes of the global DNA hypomethylation seen in cells at the origin of Akt + diuron-induced glioma." (PMID 31727122, 2019). "On the opposite, a specific inhibition of DNMT1/DMAP1 interaction increased the temolozomide response in glioma cells, suggesting that inhibition of specific DNMT-including complexes could be used in the future in combination with classical chemotherapeutic agents." (PMID 29449903, 2018). "Interestingly, DNMT1 expression was significantly correlated with overall CpG methylation level (Spearman-Ranked correlation and Fisher's Extract test for significance niveau p<0.05) in low-grade gliomas." (PMID 28036297, 2017). "Clinical correlation analysis indicated a positive correlation between DNMT1 expression and the WHO grade of glioma, with the highest expression observed in grade 4 gliomas and the lowest expression in grade 2 gliomas." (PMID 39174498, 2024). "To summarize, in glioma cells with NUP37 depletion (NC + KD), overexpression of DNMT1 (KD + OE) partially restored the proliferation, invasion, and migration of glioma, while it decreased apoptosis to varying degrees." (PMID 39174498, 2024). "To delve deeper into the role of DNMT1 in these cellular functions, we overexpressed DNMT1 in NUP37-depleted glioma cells and assessed the changes in cell functions." (PMID 39174498, 2024).
glioma (continued). "In glioma, DOK7 expression was repressed by DNMT1 and DOK7 down-regulation facilitates the proliferation of glioma cells." (PMID 38095644, 2023). "On the contrary, overexpression of DNMT1 promoted VSVΔ51 replication and suppressed IRF3/7 expression in glioma cells." (PMID 37880243, 2023). "Further study showed that the miR-21/SP1/DNMT1 positive feedback loop in MSCs triggered by glioma exosomal CD44 upregulated MSC exosomal miR-21 expression, amplifying the glioma exosomal immunosuppressive signal." (PMID 37481646, 2023). "A DNA methyltransferase (DNMT) inhibitor disrupted the DNMT1/CFP1 complex and enhanced mouse glioma chemosensitivity." (PMID 37396042, 2023). "It has been reported that DNMT1 suppresses colon adenocarcinoma hypermethylation (CAHM) and promotes tumor progression through the SPAK/JNK pathway in glioma." (PMID 35903713, 2022). "DNMT1 expression is inversely correlated with the MEG3 transcript, supporting DNMT1’s involvement in MEG3 dysregulation in gliomas." (PMID 34316694, 2021). "Through survival analysis, this study constructed a low‐grade glioma prognostic model with 4 genes (NSUN4, NSUN7, DNMT1 and NSUN6) and drew a nomogram accordingly." (PMID 33400376, 2021). "The results showed that NSUN4, NSUN7, DNMT1, DNMT3B, DNMT3A, NOP2 and NSUN5 were negatively correlated with the overall survival of low‐grade glioma, while NSUN6 was positively correlated with the overall survival." (PMID 33400376, 2021). "Both plant extracts (with IC50 concentration for grade IV glioma cells and U87MG cells) showed down-regulation of UHRF1 and DNMT1 gene expression after treatment with TR and AtPAP1 root extracts on both tested lines." (PMID 29786770, 2018). "For example, we reported that DNMT1 and DNMT3A were necessary for the methylation of the CASP8 promoter in glioma cells." (PMID 29449903, 2018). "Methylation of NF2 and DNMT1 was markedly increased, and miR-152-3p was downregulated in GBM tissues and glioma cells." (PMID 28764788, 2017). "Functionally, miR-152-3p overexpression, DNMT1 knockdown and NF2 overexpression significantly induced glioma cell apoptosis and inhibited their invasion." (PMID 28764788, 2017). "In these cell lines, we observed that DNMT1 and NF2 were significantly increased and decreased, respectively, in glioma cells compared with HEB cells." (PMID 28764788, 2017). "Both 3- and 7-day transient treatments with 100 and 200 nM DAC depleted DNMT1 levels, whereas 10 nM dose resulted in diminished levels of DNMT1 in TS603 and TS667 glioma cells." (PMID 24077826, 2013). "With their results, the authors propose that overexpression of DNMT1 and DNMT3B in gliomas is a result of a significant hypomethylation occurring in the euchromatin region of its gene promoters." (PMID 22973309, 2012). "This demonstrated that DNMT1, IDH3A, TACC3, and TKT could be incorporated as prognostic markers for glioma." (PMID 37875819, 2023). "We discovered that DNMT1 is critical for D2HG-induced IRF3/7 downregulation and may serve as a potential biomarker predicting which IDH1mut gliomas are most likely to respond to oncolytic viruses." (PMID 37880243, 2023). "CD133 knockdown increased the nuclear translocation of DNMT1 in CD133+ glioma cells without obviously changing the nuclear translocation of DNMT3a or DNMT3b." (PMID 35798319, 2022).
glioma (continued). "In glioma, lncRNAs interact with crucial regulatory RBPs like EZH2, DNMT1, and hnRNPL." (PMID 33050646, 2020). "Moreover, it has been reported that DNMT1 and DNMT3B are overexpressed in gliomas and inhibiting DNMTs by 5-azacytidine (azacytidine, DNMT inhibitor) enhances expression of tumor suppressor genes such as p21." (PMID 31500384, 2019). "OCT4 expression was shown to correlate with DNMT1 and DNMT3b expression in primary glioblastoma neurosphere, and the transgenic OCT4/SOX2 co-expression is able to increase the expressions of DNMTs in gliomas." (PMID 31771617, 2019). "Genes encoding enzymes that can directly modify DNA methylation such as TET family genes and DNMT1/3 were not altered in C.3 gliomas despite their remarkable demethylation." (PMID 30760837, 2019). "In glioma cells, DNA demethylation of promoters, following specific inhibition of DNMT1, DNMT3A, or DNMT3B, was not fully redundant suggesting the existence of different target patterns for these enzymes." (PMID 29449903, 2018). "Another study showed that the downregulation of DNMT1 by small interfering RNA could also lead to decreased MGMT expression and the subsequent sensitization of glioma cells to TMZ/Taxol." (PMID 28297578, 2017). "Interestingly, DNMT1 gene expression was increased in si-HEY1 treatment, suggesting that HEY1 can be an epigenetic target in studying glioma progression." (PMID 28574840, 2017). "The results demonstrated that DNMT1 promoter hypermethylation does not occur in low-grade gliomas, it was mainly observed in secondary glioblastomas." (PMID 22264301, 2012). "We then demonstrate that the Dnmt1 phosphorylations by Akt and/or PKC abrogate the interactions of Dnmt1 with PCNA and UHRF1 in cellular and acelluar studies including mass spectrometric analyses and the use of primary cultured patient-derived glioma." (PMID 20613874, 2010). "Moreover, we illustrated that DNMT1 overexpression, in the context of NUP37 depletion, could partially restore both the proliferation and invasion of glioma cells." (PMID 39174498, 2024). "Consistent with this hypothesis, a study performed in gliomas showed that decitabine-mediated proliferation arrest can be blocked by silencing of DNMT1, and overexpression of TERT correlated with an increase in DNMT1 levels, which improved decitabine sensitivity in the meanwhile." (PMID 35838271, 2022). "In addition, to determine whether Rc TR extract could induce the apoptosis of glioma cells, we evaluated the levels of DNA epigenetic markers such as UHRF1 and DNMT1." (PMID 30171426, 2018). "In addition, to determine whether Rc TR extract could induce the apoptosis of glioma cells, the levels of two DNA epigenetic markers, UHRF1 and DNMT1, were evaluated." (PMID 30171426, 2018). "Since our study focuses on association of DNMT1 and p-c-Jun with the G-CIMP/proneural subclass of glioblastoma, it is possible that our observed phenotype might specifically characterize this glioma subtype and would not be observed in the others." (PMID 28036297, 2017). "DNA methyltransferases DNMT3B, DNMT3A, and DNMT1 were comparatively overexpressed in the MS4A6A high expression subgroup, which might be the reason for MS4A6A hypomethylation in glioma tissues, leading to insight into upregulated mechanisms of MS4A6A in glioma." (PMID 36119086, 2022). "MiR‐148‐3p is significantly reduced in glioma tissues compared to adjacent nontumor tissues and correlated with various factors, including WHO grade, tumour size, prognosis, as well as DNMT1 and RUNX3 expressions." (PMID 40387409, 2025).